LDHA (lactate dehydrogenase A)
Diseases named in the same sentence as LDHA in open-access papers (continued):
Sharing a sentence is not in itself a finding about the gene and the disease.
tumor (continued). "Overall, lactylation is closely related to the development of tumors, and further research is needed to determine whether the anti-tumor effect of LDHA inhibitor is mediated by the regulation of lactylation." (PMID 40584617, 2025). "Understanding the regulatory nodes of the Warburg effect, such as HIF-1α and LDHA, may provide new avenues for therapeutic interventions aimed at halting tumor progression and restoring immune function 17, 30-32." (PMID 41281744, 2025). "Notably, targeting lactate production (LDHA inhibitor: sodium oxamate) synergized with RHOA-pathway inhibition (ROCK inhibitor: Y-27632) to suppress tumor progression." (PMID 41291745, 2025). "Overexpression of LDHA has been linked to chemotherapy resistance through the maintenance of cancer stem cell (CSC) stemness, mediated by enhanced lactate production and the establishment of an acidic tumor microenvironment." (PMID 41368023, 2025). "Among these, LDHA-mediated lactate accumulation represents a major source of tumor-derived lactate." (PMID 41152975, 2025). "LDHA-mediated lactate production has emerged as a critical driver of tumor drug resistance." (PMID 41152975, 2025). "An important hallmark of these highly glycolytic tumor cells is the high need for the recovery of NAD+ from NADH, which is managed by the conversion of the glycolytic end-product pyruvate towards lactate by the action of lactate dehydrogenase A (LDHA)." (PMID 40508207, 2025). "Conversely, LDHA impairment negatively affected tumor growth and metastasis formation." (PMID 40563460, 2025). "Furthermore, in mouse GBM models (GL261/CT2A), LDHA silencing has been shown to inhibit tumor growth and prolong survival." (PMID 41463052, 2025). "Since LDH activity directly governs intracellular and extracellular lactate levels, pharmacological inhibition of LDHA may influence the extent of protein lactylation in tumor cells." (PMID 40948941, 2025). "Notably, there is strong synergy between the clinically available LDHA inhibitor stiripentol and genotoxic therapies, such as cisplatin and ionizing radiation (IR), which can reduce tumor resistance to these treatments." (PMID 40057816, 2025). "Increased levels of oxalacetate, in turn, competitively inhibit LDHA in tumor cells." (PMID 40801609, 2025). "Similarly, inhibitors of lactate dehydrogenase A (LDHA) and monocarboxylate transporters (MCTs) disrupt lactate metabolism, reducing acidification of the tumor microenvironment and impairing tumor survival." (PMID 40486584, 2025). "They found that lactate dehydrogenase (LDHA), responsible for lactate production, was one of the most upregulated proteins in drug‐resistant tumours, and lactate was one of the most abundant metabolites in these tumours." (PMID 41020792, 2025). "LCA can inhibit the STIP1/AHCY/LDHA axis and inhibit tumor development mediated by the gly." (PMID 41163796, 2025). "Furthermore, LDHA-EV administration markedly increased LDHA, lactate, and ATP levels in the local tumor region, while GNE140 reversed these effects." (PMID 40093910, 2025). "Moreover, tyrosine phosphorylation of PKM2 induces the Warburg effect, and phosphorylation of LDHA regulates redox metabolic homeostasis; both studies highlight the role of lactate in regulating the tumor microenvironment during metabolic reprogramming." (PMID 40416986, 2025). "Moreover, LDHA overexpression enhanced lactate production in tumor cells, completely offsetting the effects of circSMPD4 knockout, while LDHA knockdown in circSMPD4‐overexpressing cells yielded similar conclusion." (PMID 40940312, 2025).
tumor (continued). "Clinical retrospective studies-large in number have further shown serum and bile lactate levels-high, combined with tumor tissues’ LDHA expression-elevated, exhibit strong correlations with pathological grading-systems, clinical staging-criteria, and prognosis-outcomes in GBC cases." (PMID 41458606, 2025). "GLUT3 may facilitate tumor growth and metastasis by modulating Lactate dehydrogenase A(LDHA) activity." (PMID 40977700, 2025). "Overexpression of LDHA in GC cells enhances glycolytic flux, contributing to tumour progression." (PMID 41154605, 2025). "Additionally, LDHA-mediated lactate production impaired tumor immune surveillance by T cells and NK cells." (PMID 41035644, 2025). "The research explored what LDHA plays in mediating tumor drug resistance across therapies." (PMID 41422325, 2025). "Moreover, it has been reported that the antiepileptic drug stridently reduces lactylation of NBS1 at K388 by inhibiting LDHA, thus overcoming chemoresistance in tumor cells." (PMID 41373440, 2025). "Intriguingly, recent evidence suggests that LDHA inhibition may also modulate the tumor microenvironment by promoting anti-tumor immune responses, providing a rationale for combination with immune checkpoint blockade." (PMID 40593465, 2025). "LDHA, a key enzyme in glycolysis, can suppress glycolysis and tumor growth when inhibited." (PMID 40944197, 2025). "Tumor cell migration and proliferation were inhibited by LDHA downregulation, suggesting that it may be a useful target for therapy." (PMID 39968078, 2025). "Additionally, silencing of KLF13 raised the protein levels of SH2B1, IRS1, GLUT1, PDK1, and LDHA in xenograft tumours, and KLF13 overexpression exhibited the reverse actions." (PMID 41410190, 2025). "Furthermore, elevated LDHA expression correlates significantly with tumor size, clinical stage, and histological grade and is inversely associated with disease-free survival and overall survival in clear cell renal cell carcinoma patients." (PMID 41368023, 2025). "As one of the key enzymes involved in glycolysis, LDHA in T cells may affect the immune escape of the tumor cells." (PMID 40244859, 2025). "Additionally, some research has indicated that LDHA inhibitors in conjunction with BRAF inhibitors have demonstrated notable anti-tumor activity in ATC therapy." (PMID 40917751, 2025). "Additionally, Triptolide suppresses key metabolic enzymes such as LDHA, limiting lactate-driven tumor adaptation." (PMID 40770810, 2025). "More importantly, the inhibition of lactate production via an LDHA inhibitor or TPX2 lactylation significantly suppressed in vivo HCC tumour growth, suggesting that TPX2 lactylation may serve as potential targets for new cancer interventions." (PMID 40107714, 2025). "Targeting LDHA or H3K9 lactylation may reduce tumor growth and improve chemotherapy sensitivity by enhancing immune responses." (PMID 41458606, 2025). "The necessity for tumor-selective delivery systems (such nanocarrier-loaded LDHA inhibitors) or dual-target medications (like simultaneous inhibition of LDHA and HDAC) is highlighted by the danger of systemic metabolic disruptions associated with current LDH/MCT-targeting therapies." (PMID 41267990, 2025). "By activating the DIO3OS/PTBP1/LDHA cascade, tumor cells may gain metabolic flexibility, enabling them to survive AI therapy." (PMID 40303296, 2025). "Inhibiting LDHA reduces lactate production and aids tumor treatment." (PMID 40137165, 2025). "Furthermore, studies have shown that the combination of LDHA inhibitors with anti-PD-1 therapy can significantly reduce the tumor volume in a mouse orthotopic BCa model compared to the use of anti-PD-1 therapy alone." (PMID 40426972, 2025). "Extracellular vesicles carrying LDHA enzyme preferentially accumulate in tumor regions and providing ATP and enhanced lactate level may an important reason for the EV brain-targeting and contribute to the tumor progression." (PMID 40093910, 2025).
tumor (continued). "Through various in vivo and in vitro HCC models, we comprehensively demonstrated that circSMPD4 promotes tumor lactate metabolic reprogramming by inhibiting LDHA degradation through CMA‐lysosome pathway, ultimately inducing NK‐cell‐related immune escape and enhancing HCC malignancy." (PMID 40940312, 2025). "Some studies have reported that zinc ions could inhibit tumor growth by inhibiting the activity of enzymes in glycolysis including lactate dehydrogenase A (LDHA) and hexokinase II (HK2), disrupting redox metabolism, and activating the cGAS-STING pathway." (PMID 40284443, 2025). "In our study, we mentioned that EVs from infiltrating tumor cells in the brain tissue surrounding exhibited strong stemness may also release LDHA enriched EVs and regulated by TMZ/radiotherapy post-operation." (PMID 40093910, 2025). "Thus, the S-palmitoylation of LDHA for tumor cells minimizes oxidative stress, allowing cell survival and proliferation, especially under metabolic or hypoxic stress conditions." (PMID 40335986, 2025). "In cancer therapy, selectively targeting this system, via LDHA inhibition and modulation of iron availability, may sensitize tumor cells to ROS-induced cytotoxicity." (PMID 40663910, 2025). "Additionally, increased NAT10 expression promotes glycolysis in tumor cells by stabilizing YTHDC1, PFKM, and LDHA mRNA, thus providing essential energy support for tumor growth." (PMID 39897026, 2025). "In our prior experiments, we found that NDRG1 influences tumor cell metabolic functions by regulating glycolysis and xoxidative metabolism, particularly in A549 cells, where it synergistically interacts with LDHA to promote lactate production and alter the acidic microenvironment of tumor cells." (PMID 40539245, 2025). "As a result, LDHA inhibition by Oxamate disproportionately disrupts energy production in cancer cells, supporting the concept that targeting the glycolytic phenotype can selectively impair tumor cells while sparing normal tissues." (PMID 40565174, 2025). "The potential of LDHA as a tumor therapeutic target is strongly supported by these findings." (PMID 39897050, 2025). "Furthermore, LDHA proved essential for circSMPD4‐mediated promotion of tumor invasion and proliferation." (PMID 40940312, 2025). "Furthermore, acting as a key regulator, Myc drives the expression of numerous glycolysis-related genes through direct transcriptional upregulation, including LDHA, significantly enhancing tumor cell glycolytic capacity." (PMID 41561760, 2025). "This restraint of LDHA enzymatic activity inhibited tumor progression and resistance to RAI in PTC." (PMID 39934144, 2025). "Moreover, recent investigations have accentuated the regulatory function of LDHA in tumor immune response." (PMID 39897050, 2025). "Similarly to the subcutaneous transplantation model, the tumor specimens generated from the KO cells showed upregulated LDHA expression, decreased CD8+ T cell infiltration, and increased Foxp-3+ Treg cell infiltration." (PMID 40139191, 2025). "Moreover, LDHA serves as a biomarker for tumor diagnosis and prognosis, making it an attractive target for potential pharmacological interventions in cancer treatment." (PMID 38731521, 2024). "Furthermore, we also revealed the link of LDHA expression with immune subtypes, tumor stemness and drug resistance." (PMID 38709280, 2024). "In this study, we analyzed the expression pattern and prognostic value of LDHA in pan-cancer and explored its association between tumor microenvironment (TME), immune infiltration subtype, stemness scores, tumor mutation burden (TMB), and immunotherapy resistance." (PMID 38709280, 2024). "Combing with the previous findings, we concluded that LDHA may play a role in monitoring anti-tumor immunotherapy by modulating TME composition and immune responses." (PMID 38709280, 2024).
tumor (continued). "In addition, in adoptive immunotherapy, eliminating LDHA at the germline level produces T-cell offspring with limited anti-tumor function, and the temporal regulation of LDH activity is one of the important factors to consider." (PMID 39464313, 2024). "Disruption of LDHA activity to prevent lactate generation in tumor cells might have uncontrollable side effects." (PMID 38983918, 2024). "Additionally, the inhibition of LDHA can effectively decrease both the degree of lactylation and the tumor burden." (PMID 38983918, 2024). "FX-11, a specific LDHA inhibitor, exhibited anticancer effects in a mouse tumor model and may be a target for cancer treatment." (PMID 38983918, 2024). "Furthermore, the combination of LDHA inhibition and Lobaplatin treatment demonstrated a synergistic effect, significantly inhibiting tumor growth and highlighting the potential of LDHA as a therapeutic target to overcome drug resistance in LUAD." (PMID 39680520, 2024). "Consequently, LDHA not only serves as a biomarker for tumor diagnosis and prognosis but also represents an ideal target for tumor therapy." (PMID 38731521, 2024). "In this study, we found that LDHA expression was correlated with cancer stage, metastasis, invasion, immune regulation, etc., suggesting that it may be an independent predictor of tumor." (PMID 38709280, 2024). "Tumor cells with inactive LDHA exhibit slower proliferation due to reduced ATP release." (PMID 38715141, 2024). "The results confirmed the repressive effect of LDHA knockdown on tumor growth." (PMID 38627278, 2024). "Moreover, the animal experiments further confirmed that KIAA1429 silencing diminished levels of YTHDF1, FOXM1, HK2, ENO1, and LDHA and suppressed tumor growth." (PMID 39060874, 2024). "Therefore, tumor cell expression of LDHA as well as the adaptive immune system are both essential for the antitumor effect of LDHA inhibition." (PMID 39225102, 2024). "Subsequently, the impact of LDHA expression on tumor growth was investigated by knocking down Ldha in CT26 murine tumor cells and inoculating them into immunodeficient (BALB/c nude) mice for in vivo studies, revealing significantly restricted tumor growth in the shLdha group." (PMID 39107297, 2024). "In addition to the classical intracytoplasmic lactate catalytic activity, LDHA displays nuclear translocation in several types of tumor cells." (PMID 39587076, 2024). "Of note, NK cells were revealed to elevate tumor-killing activity after LDHA knockdown, indicating that LDHA may contribute to tumor immune escape by impairing immune cell function." (PMID 38627278, 2024). "Here, a multifaceted bioinformatics analysis was conducted to investigate the correlation of LDHA expression patterns in various cancers with the corresponding tumor prognosis and stage, and we reveled that the prospect of LDHA in cancer diagnosis is worthy of expectation." (PMID 38709280, 2024). "Notably, elevated LDHA expression correlated with adverse clinical survival and escalated tumor grade, especially in advanced stages." (PMID 39394200, 2024). "We observed variations in LDHA CNV rates among patients with different tumor types." (PMID 38198170, 2024). "Furthermore, flow cytometry analysis showed that CD8+ T cells in the sh-LDHA groups had a stronger capacity for anti-tumor activity and proliferation, and macrophages were more inclined to antitumoral M1 polarization than those in the sh-NC group." (PMID 38664705, 2024). "We also demonstrated functional overreliance on glycolysis by tumor cells compared with T cells, both in vitro using human and mouse cells and ex vivo from murine syngeneic tumor models, identifying a therapeutic window for preferentially targeting LDHA in tumor cells." (PMID 39225102, 2024).
tumor (continued). "In the TIMER2.0 database, LDHA expression level was negatively related to the infiltration levels of memory B cell, myeloid DC, activated mast cell, and NK T cell, which inhibit the tumor progression and benefit patients’ prognosis." (PMID 39582531, 2024). "In addition, HK2, ENO1, and LDHA mRNA levels were strikingly reduced in tumor tissues after KIAA1429 silencing (all P < 0.05)." (PMID 39060874, 2024). "Genetic dampening of tumor LDHA decreases glucose consumption and lactate production by tumor cells, and this was associated with slower tumor progression, higher CD8+ T cell infiltration, and improved overall survival in preclinical models of various solid tumors." (PMID 39225102, 2024). "Besides, HK2, LDHA and Ki67 positive cells also were decreased in the tumor tissues of sh-circ_0000376 group." (PMID 38218855, 2024). "In support of our data, LDHA has been reported to promote cancer proliferation, survival, invasion and metastasis by regulating cellular ATP levels, modulating cancer stem cell phenotypes and protecting the tumour from reactive oxygen species damage." (PMID 38372449, 2024). "In addition, the results of IHC analysis showed that the expressions of CD8, GLUT1, HK2, PKM2 and LDHA were significantly up-regulated in tumor tissues treated with anti-TIGIT mAb." (PMID 38216949, 2024). "PDX tumor analysis displayed also an extremely downregulation of LDHA in vitamin C treated tumors." (PMID 38425123, 2024). "Therefore, the inhibition of endogenous lactate production and transport‐related enzymes, such as MCTs and LDHA, is useful for tumour treatment." (PMID 39417674, 2024). "Previous studies have shown that HIF−1α directly induces the expression of many metabolic genes in cancer cells to enhance aerobic glycolysis, such as glucose transporters (GLUTs), pyruvate dehydrogenase kinase 1 (PDHK1), lactate dehydrogenase A (LDHA), to meet the energy needs of tumor growth." (PMID 38654163, 2024). "In tumor cells, LDHA facilitates lactate production due to their reliance on enhanced glycolysis for energy, supporting rapid tumor growth and division; pyruvate generated from glutamine metabolism is also converted into lactate via LDHA." (PMID 39766353, 2024). "In addition, we found that as the pTNM stages advanced and tumor metastasis, oxalate and its metabolic key enzyme LDHA changed in LUAD." (PMID 38567154, 2024). "LDHA was strongly expressed in tumor tissues compared to normal tissues at mRNA and protein levels." (PMID 38764020, 2024). "LDHA expression had a positive correlation with tumor purity, B cells and neutrophils in ACC." (PMID 38709280, 2024). "As reported, LDHA not only is correlated with TIME but also directly regulates tumor growth." (PMID 38627278, 2024). "Consequently, the research and development of anti-tumor drugs targeting LDHA have garnered significant attention." (PMID 39596288, 2024). "LDHA and LDHB are elevated in many tumor types and are associated with tumor growth and invasion." (PMID 38291366, 2024). "The data confirmed that LDHA knockdown substantially repressed tumor growth in mice." (PMID 38627278, 2024). "One study showed that targeting LDHA with siRNA or small molecule inhibitors increased oxygen consumption and reactive oxygen species production, reduced glucose uptake and lactate production, and decreased tumor cell growth." (PMID 38773429, 2024). "For example, the factors contributed to the LDHA downregulated in tumor samples remains unclear, and the mechanism of CENPE as a carcinogenic factor positively regulating the immune cells was not clarified." (PMID 37925501, 2023). "LDHA silencing exposed a connection between glycolysis and tumor preservation." (PMID 37398901, 2023). "This may reflect the change in tumor burden, as seen in a previous study showing that LDHA is overexpressed in PTC tissue and represents aggressive PTC behavior." (PMID 37158852, 2023).